EGFR (epidermal growth factor receptor)
Diseases named in the same sentence as EGFR in open-access papers (continued):
Sharing a sentence is not in itself a finding about the gene and the disease.
tumor (continued). "The significance of EGFR tumor expression is unclear, with two studies demonstrating either high or low EGFR scores associated with better survival." (PMID 23970998, 2013). "After 1, 2, and 3 months in culture, we analyzed the tumor cells under the different conditions for the presence of EGFR amplification and expression, by FISH and immunohistochemistry, respectively." (PMID 24349039, 2013). "Our data demonstrated that the majority cases of penile SCC are associated with over-expression of EGFR and loss of expression of RASSF1A, a potential tumor suppressor." (PMID 23637996, 2013). "Quantization of EGF-NIR in tumors, normalized to skeletal muscle and compared to its level in the liver, indicated a faster accumulation of the agent in the tumor, compared to liver, suggestive of a specific EGFR mediated process." (PMID 23857061, 2013). "Treating an EGFR-addicted tumor with an anti-EGFR agent creates a selection pressure favoring the survival of those cells that are able to avoid the effect of the drug; that is, those cells that find an escape mechanism to satisfy their addiction." (PMID 23637683, 2013). "Selective interaction of [125I]PYK with EGFR-TK on A431 tumor cell membranes was confirmed by pretreatment experiments with various EGFR-TK and other tyrosine kinase inhibitors." (PMID 23494210, 2013). "For this, we analyzed the untreated and treated tumor tissues to check the activation status of EGFR and its pathway members, AKT, STAT3 and ERK1/2, as well as the mitochondrial caspase-cascade." (PMID 23555785, 2013). "There is direct communication between macrophages and tumor cells importantly mediated by interactions between EGFR-CSF-1 and CXCR4-EGF." (PMID 23762835, 2013). "The most dramatic difference was found in GBM6, an EGFRviii mutant tumor, followed by GBM10 and GBM14, which both harbor PTEN mutations but wild type EGFR." (PMID 23801022, 2013). "The feasibility of targeting EGFR for tumor imaging has been experimentally demonstrated using 18F or 11C-labeled EGFR-TK inhibitors; however, these labeled compounds were also observed to produce high radioactivity in the blood and peripheral tissues." (PMID 23494210, 2013). "Primary human monocytes and macrophages respond to tumor cell-derived factors by secreting EGFR- and STAT3-activating ligands, thus inducing two important oncogenic pathways in carcinoma cells." (PMID 23597096, 2013). "Both the EGFR-IL and hIgG-IL used in this study were slightly anionic, but not to an extent that would affect the efficiency of drug delivery to the tumor." (PMID 24175095, 2013). "Therapies such as monoclonal antibodies and tyrosine kinase inhibitors targeting EGFR have demonstrated limited anti-tumor efficacy; however, reports of combined targeting of EGFR and STAT3 are few." (PMID 24499623, 2013). "Our preliminary studies showed that LMP1 is involved with several signal transduction pathways, including the EGFR, which triggers the activation of several different target genes to affect the biological behavior of tumor cells." (PMID 23472069, 2013). "EGFR mutation is a somatic mutation, the detection of which requires a highly specific and sensitive method, for EGFR mutant cells are mixed with wild type cells in the tumor sample." (PMID 24351833, 2013). "Cetuximab, a monoclonal antibody against EGFR, has been successful at prolonging survival but has only a 10% tumor shrinkage response rate in a clinical setting." (PMID 23405260, 2013). "mRNA levels of EGFR were significantly higher in tumor tissues than in non-tumor tissues and the overexpression rate was 35.4%." (PMID 23785399, 2013). "During the course of therapeutic intervention, we also observed a significant increase in tumour microglia infiltration upon treatment with EGFR inhibitor, suggesting that inhibition of EGFR alters the tumour microenvironment." (PMID 26082317, 2013).
tumor (continued). "Cetuximab (C) is a chimeric monoclonal antibody (MoAb) that binds to the EGFR and blocks the EGFR signaling cascade, thus inhibiting the growth of the tumor." (PMID 24312376, 2013). "The primary objective was to assess the objective response rate (ORR), while EGFR and KRAS mutations and mRNA and protein expression levels of ERCC1 and RRM1 were analyzed in tumor tissues and blood samples." (PMID 23621919, 2013). "The significant association of reduced CDC25A expression with overexpression of p-EGFR in this tumor suggests their synergistic action in development of tumor." (PMID 23675485, 2013). "Earlier transcriptional profiling studies have shown that cyclin D1 is a critical downstream effector of EGFR signaling and EGF-stimulated cyclin D1 expression is closely associated with tumor development caused by enhanced cell survival and proliferation." (PMID 24340049, 2013). "Although tumor tissues have been shown to over-express EGFR protein, cancer patients often show a decrease (40%–60%) in serum EGFR ECD levels compared to normal control subjects." (PMID 23990977, 2013). "Recently, EGFR has been found to be a validated target for cancer chemotherapy to treat different tumours." (PMID 23935985, 2013). "Among the three biomarkers, EGFR mutations are the strongest predictive biomarker for PFS and tumor response to first-line gefitinib vs. CBDCA + PTX." (PMID 23361373, 2013). "The introduction of EGFR TKIs as first-line treatment has been generally accepted to improve tumor response rates and PFS in patients with advanced NSCLC harboring EGFR mutations compared to standard chemotherapy." (PMID 24376677, 2013). "The immunohistochemical analysis revealed marked positive expression of EGFR in the tumor tissues of all groups and the positive signals were distributed in the cytoplasm and membrane." (PMID 23833649, 2013). "In particular, we need to gain a deeper knowledge on the relevance of EGFR addiction for tumor initiating cells." (PMID 23637683, 2013). "Several research groups described recently the construction, selection, and use of EGFR-binding sdAbs for tumor targeting, active drug delivery and radioimmunodetection of EGFR overexpressing tumors." (PMID 24161153, 2013). "The authors sequenced exons 18–21 of the EGFR gene using DNA extracted from tumor and normal lung tissue obtained at a previous resection: the L858R mutation was detected." (PMID 23340652, 2013). "In contrast, cetuximab Fab fragments were able to bind to tumor cells with lower EGFR expression levels." (PMID 23637683, 2013). "The blockade of Raf signaling which is the main effect of sorafenib can lead to the repression of transforming growth factor α-epidermal growth factor receptor autocrine loops of tumor cells." (PMID 23588838, 2013). "Epidermal growth factor receptor tyrosine kinase (EGFR-TK) represents an attractive target for tumor diagnosis agents." (PMID 23494210, 2013). "EGFR is the most frequently amplified gene and a primary contributor to tumor initiation and progression in GBM." (PMID 23977117, 2013). "FcαRI Tg PMNs also lysed tumour cells with both IgA1 and IgA2 EGFR, however, lysis induced by IgA2 EGFR was more efficient." (PMID 23918228, 2013). "In our study, EGFR-TKI treatment suppressed tumor proliferation and improved PS and quality of life." (PMID 23566546, 2013). "In situ PLA has been utilized in studies investigating both EGFR dimerization and receptor activation, which has been proposed to play a crucial role during tumor progression, and also the development of drug resistance." (PMID 24199171, 2013). "Different EGFR-expressing tumor cells (SCC-1, 22B, A549, and HT-29) were pretreated with gefitinib, and then with 125I-hEGF or 125I-Vectibix (an anti-EGFR monoclonal antibody)." (PMID 23748900, 2013).
tumor (continued). "Amongst others, YB-1 activates gene expression of the epidermal growth factor receptor (EGFR), matrix metalloproteinase 2 (MMP-2) and of the receptor tyrosine kinase c-MET, all this associated with tumor cell adhesion, invasion and metastasis." (PMID 24044901, 2013). "Several studies have shown that EGF, by activating EGFR, leads to increased cell migration, a feature of tumour progression, metastasis and wound healing but in other cell-types leads to increased cell proliferation." (PMID 23593160, 2013). "Because of the apparent role of EGFR in tumor aggression and poor prognosis, and its high expression in many types of cancers, the EGFR pathway has been well investigated as a possible target in cancer therapies." (PMID 23748900, 2013). "The response associated with EGFR mutations is thought to be due mainly to an “addictive” dependence of tumor cells on the EGFR signaling pathway for survival." (PMID 24252457, 2013). "Methylation also interplays with phosphorylation signaling at the cell surface, negatively modulating EGFR signaling and influencing tumor model progression in vivo." (PMID 23505349, 2013). "We stained tumour cell-bound EGFR antibodies using anti-kappa-light chain antibodies, with or without addition of extra EGFR antibodies ex vivo." (PMID 23918228, 2013). "Further, it has been demonstrated that the expression of a specific mutant form of EGFR (EGFRvIII) promotes tumor formation and growth." (PMID 23555046, 2013). "Nevertheless, IgA2 EGFR was more effective in FcαRI Tg than in WT mice, indicating the contribution of Fc-mediated effector mechanisms to the anti-tumour effects." (PMID 23918228, 2013). "Of the 24 FMAs 15 (62.5%) had EGFR positive tumor cells with weak (1+) labeling in 9 cases (60%) and moderate (2+) labeling in 6 cases (40%)." (PMID 24004841, 2013). "As we have demonstrated in vitro, the α-emitter 213Bi coupled to the anti-EGFR antibody matuzumab efficiently kills hypoxic tumor cells." (PMID 23724085, 2013). "The epidermal growth factor receptor (EGFR) gene plays a key role in tumor survival, invasion, angiogenesis, and metastatic spread." (PMID 23555641, 2013). "Statistical analysis demonstrated that RIOK2 expression was significantly correlated with EGFR status in tumor specimens, although some EGFR-negative tumors also showed RIOK2 immunoreactivity, while some EGFR-negative tumors did not." (PMID 23459592, 2013). "The results suggest that siRNA mediated co-silencing of EGFR and Rictor inhibits tumor cell migration in U251MG and LN229." (PMID 23555046, 2013). "A recent study demonstrated that localization of EGFR in lipid rafts enhanced the resistance of tumor cells to gefitinib." (PMID 24354805, 2013). "Cetuximab (Erbitux, Merck-Serono, Darmstadt, Germany) is a chimeric monoclonal antibody (IgG1) that binds to the ectodomain of the human EGFR and competitively inhibits ligand binding to suppress tumor proliferation." (PMID 23824671, 2013). "ΔEGFR and other constitutively active mutant forms of EGFR found in GBMs potently drive tumor cell survival, migration, and proliferation." (PMID 23459592, 2013). "An important mediation mechanism of melatonin on the inhibitory action of the circadian-dependent growth of the tumor is the suppression of the epidermal growth factor receptor (EGFR) and of the activity of the mitogen-activated protein kinase, (MAPK)." (PMID 23348932, 2013). "In GC, higher levels of EGF, TGF-α, and EGFR correlate with advanced tumor stage and a poor clinical outcome." (PMID 24454509, 2013). "This antibody blocks binding of the normal ligands for EGFR, and thus inhibits ligand-induced activation as well as cell proliferation and orthotopic tumor growth." (PMID 23894364, 2013). "The investigation of EGFR and its signaling pathway is, therefore, important in research concerning the tumor biology of this entity." (PMID 23449029, 2013).
tumor (continued). "Tumor EGFR expression at baseline was evaluated for 18 patients (13 from the nimotuzumab arm and 5 from the control arm)." (PMID 23637683, 2013). "EGFR signaling was shown to promote tumor cell proliferation and survival, invasion and angiogenesis and mediate resistance to treatment, including ionizing radiation in preclinical models." (PMID 23874590, 2013). "We confirmed in tumor cell lines from different origins that treatment with EGFR inhibitors results in a transient upregulation of phospho-AKT under conditions of co-activation of the EGFR and Met pathways." (PMID 23812422, 2013). "These deregulated molecular events are characteristic for malignant cells, and aberrant regulation of EGFR activates downstream signals including ERKs and Akt resulting in increased tumour cell proliferation, survival, and invasiveness." (PMID 23527233, 2013). "The expression levels of TGFα, EGF, and EGFR have been shown to correlate with progressive tumor growth, development of metastasis, and resistance to chemotherapy." (PMID 23986907, 2013). "At the tumour level, somatic mutations in EGFR, KRAS, BRAF, PTEN and PIK3CA are associated with poor response to anti-EGFR therapy in CRC." (PMID 24152305, 2013). "[125I]PYK showed high tumor accumulation and selective EGFR-TK binding and also succeeded in delivering high contrast imaging of tumors." (PMID 23494210, 2013). "After 24 h, about 80% of the fluorescence signal cleared, and after 48 h the signal intensity fell to background level, except in tissues expressing EGFR tumor, bladder and liver." (PMID 23857061, 2013). "In vitro experiments confirmed that over-expression of EGFR caused transformation of NIH-3T3, Rat-1 and NRK cells and blocking EGFR activation inhibited proliferation of some tumor cells." (PMID 23613900, 2013). "In recent years, we and others described a novel NIR bio-imaging approach for CRC models using EGF-NIR which binds and visualize the heterogeneous expression of EGFR in CRC preclinical human tumor cell lines and clinical tissues." (PMID 23857061, 2013). "C225 was originally characterized for its ability to block ligand binding to the EGFR, to arrest cell proliferation and to promote tumor killing." (PMID 23894364, 2013). "EGFR activates downstream signaling cascades that promote tumor cell survival, proliferation and migration." (PMID 24349829, 2013). "The inhibition of tumor cell proliferation following the expression of AnxA6 in AnxA6-low cells has been shown to be partly due to the inactivation of activated EGFR and the termination of EGFR-mediated activation of the Ras pathway." (PMID 24354805, 2013). "The subcutaneous xenografts (n = 3 for each tumor model) were harvested for assessment of EGFR protein expression." (PMID 23710458, 2013). "Mig6 cytoplasmic expression and EGFR membranous expression were analyzed in tumor cells using a score calculated intensity (0–3+) multiplied by extension of expression (0–100%; range 0–300)." (PMID 23935914, 2013). "To verify that inhibition of EGFR activity affected the invasiveness of tumor cells, we performed detailed cell counts, which revealed less invasive cells in cortical areas within the EGFR-CD533 group compared to the control group." (PMID 23429996, 2013). "EGFR mRNA content was lower in tumor tissue (p < 0.0001), while EGFR protein was similar in tumor and mucosa samples." (PMID 24171795, 2013). "Owing to tumor heterogeneity and limitations of needle biopsy, the small amount of tissue from needle biopsies may not be emblematic of the complete pictures of tumors, leading to false negative results; while adequate surgical samples can provide enough DNA for EGFR mutation detection." (PMID 24351833, 2013). "In comparison with previous reports of EGFR imaging agents, the results of our in vivo PET imaging studies with morpholino-[124I]IPQA in mice bearing four tumor xenografts expressing different levels of phosphorylated EGFR are more selective." (PMID 23956990, 2013).
tumor (continued). "In theory, EGFR proteins on cell membrane or in cytoplasm play different roles in tumor cells and have different interaction with TKIs." (PMID 23536868, 2013). "The results of the tumor growth curve assay showed that the tumors in mice treated with CIK cells directed by the EGFR/CD3 BsAb grew significantly slower than those in the other groups (P<0.05)." (PMID 23833649, 2013). "An EGFR-dependent human tumor xenograft model (A431) was established in female BALB/c athymic mice, which were divided into three groups: one control group and two treatment groups." (PMID 24191959, 2013). "The immunohistochemical assays revealed that EGFR expression was common in tumor tissues and the positive signals were distributed in the cell membrane and cytoplasm." (PMID 23833649, 2013). "Also, after the initial course of treatment with EGFR inhibitors, repetitive imaging with such a selective radiotracer could be used for monitoring the development of tumor lesions with acquired mutations (i.e., T790 M) conferring resistance to EGFR inhibitors." (PMID 23956990, 2013). "We verified that this phenomenon appeared in different EGFR-expressing tumor cells (A549, 22B, HT-29, and SCC1) after gefitinib treatment." (PMID 23748900, 2013). "Here, the treatment of EGFR-positive tumor cells with scFv:TRAIL inhibited EGFR-mitogenic signaling and simultaneously induced TRAIL-apoptotic signaling." (PMID 23840967, 2013). "In our study, western blot was performed with different EGFR-expressing tumor cells (SCC-1, 22B, A549, and HT-29) to detect the effects of gefitinib on EGFR expression and receptor phosphorylation." (PMID 23748900, 2013). "The data seem to suggest the higher activity of EGFR via higher expression drives the oncogenic transformation in these tumors, and therefore its inactivation by cetuximab thus inhibits tumor growth." (PMID 24141978, 2013). "For these tumours, evidence derived from in vitro analysis suggests that resistance can be overcome by coupling anti-EGFR-agents with mTOR inhibitors." (PMID 22240798, 2012). "The MBED allows the required dose per fraction to be estimated when tumour radiosensitivity is reduced because EGFr is over-expressed." (PMID 22713695, 2012). "No statistically significant relation was found between local recurrence and patient age, tumor size, tumor type, EGFR expression." (PMID 22300665, 2012). "A high tumor co-expression of GPR30 and EGFR was significantly associated with a poorer progression-free survival (p<;0.001)." (PMID 23163984, 2012). "If erlotinib is to become a standard therapy for patients who have EGFR wild-type tumours and are unsuitable for chemotherapy (93% in our trial) it should be in a selected population." (PMID 23078958, 2012). "Epidermal growth factor receptor positivity was associated with high-grade carcinomas (P<0.001), tumour-size (P=0.003), lymph node metastases (P=0.003) and advanced (III, IV) tumour stage (P<0.001)." (PMID 22240798, 2012). "Membrane EGFR expression in tumor cells was also heterogeneously distributed in respect to the proportion of positive tumor cells and staining intensity." (PMID 22475688, 2012). "We found in the simulation that when CTL is added, the EGFR concentration in the tumor cell cytomembranes (EGFR_s) rises." (PMID 22394427, 2012). "REGN1400 strongly inhibits the growth of tumor xenografts in a dose-dependent manner both as single agent or in combination with anti EGFR or anti HER2 antibodies." (PMID 22889873, 2012). "The first step on this path is to start to precisely and reliably quantitate tumor expression of EGFR as a means of determining whose tumors express therapeutically-responsive levels of the EGFR protein." (PMID 22554165, 2012).